CCL14 (C-C motif chemokine ligand 14)
Diseases named in the same sentence as CCL14 in open-access papers (continued):
Sharing a sentence is not in itself a finding about the gene and the disease.
intestinal cancer (1 paper, 2023). "Cochrane’s Q test did not provide evidence of heterogeneity between CCL14 (p = 0.768, p = 0.808), CCL22 (p = 0.502), CCL28 (p = 0.175), CXCL12 (p = 0.530) and CXCL14 (p = 0.534) and intestinal cancer." (PMID 38075694, 2023).
kidney injury (1 paper, 2024). Trauma to the kidney. "The association of CCL14 with PS-AKI and non-recovery distinguishes this AKI biomarker from others, including Kidney Injury Molecule-1 and neutrophil gelatinase-associated lipocalin, which are early markers of kidney injury." (PMID 38666354, 2024).
lymph node metastasis (1 paper, 2024). "In contrast, the expression of CCL14 did not significantly differ according to race, age, lymph node metastasis status, or distant metastasis status." (PMID 39030403, 2024).
myeloma (1 paper, 2015). "We found that chemokines CCL3, CCL14, and CCL2 were highly expressed by myeloma and BM cells, and the levels of CCL14 and CCL3 in myeloma BM positively correlated with the percentage of BM-infiltrating MΦs." (PMID 26155942, 2015).
neuroendocrine carcinoma (1 paper, 2024). A malignant neuroendocrine neoplasm composed of cells containing secretory granules that stain positive for NSE and chromogranin. "On the other hand, some chemokines such as CCL28 and CCL14 were downregulated in high-grade neuroendocrine carcinoma compared to normal tissue." (PMID 39097562, 2024).
Obesity (1 paper, 2023). Accumulation of substantial excess body fat. "In humans, cytokine profiles in the blood can be reversed after bariatric surgery—elevated CCL14, soluble vascular endothelial growth factor receptor 2 (VEGFR2), and platelet-derived growth factor BB in obesity are reduced, and lower CXCL12, CCL11, and CCL27 in obesity are increased." (PMID 38037591, 2023).
pancreatic cancer (1 paper, 2023). "By performing a K–M survival analysis, CCL5 and CCL14 are associated with survival in patients with pancreatic cancer." (PMID 37741887, 2023). "Here, we found that changes in the expression of CL5 and CCL14 were consistent in pancreatic cancer, while they had opposite prognostic effects." (PMID 37741887, 2023).
renal dysfunction (1 paper, 2023). "A multi-center international study to identify biomarkers of the persistence of KDIGO stage 3 AKI in ICU patients with AKI KDIGO stage 2 or 3 found that higher levels of urinary C-C motif chemokine ligand 14 (CCL-14) predicted the persistence of renal dysfunction." (PMID 37892163, 2023).
sarcoidosis (1 paper, 2020). Sarcoidosis is a multisystemic disorder of unknown cause characterized by the formation of immune granulomas in involved organs. "Interrogation of the expression levels of these 10 sarcoidosis genes to TB and CM DEGs revealed CCL14, CXCL9, FABP4, NR1H3 were also significantly dysregulated in TB." (PMID 33276795, 2020).
viral infection (1 paper, 2024). "CCL14 and CD7 were among some of the most decreased proteins in viral infection." (PMID 37831367, 2024).
tumor (48 papers, 2010 to 2026). "In these malignancies, CCL14 expression was generally downregulated in tumor tissues and associated with better survival outcomes and less advanced disease." (PMID 39030403, 2024). "We found that CCL14 expression was positively associated with tumor-infiltrating immune cells (TIICs) and particular immune cell genetic changes in LUAD TIICs are strongly associated with tumor progression, therapy and prognosis." (PMID 39030403, 2024). "Our objectives were to study the association between CCL14 and tumor-infiltrating immune cells (TIICs) as well as the predictive significance of CCL14 in LUAD." (PMID 39030403, 2024). "Meanwhile, CCL14 low expression in HCC tumor tissues is associated with a poor prognosis (P = 0.035)." (PMID 31641099, 2019). "CCL14 is a tumor suppressor associated with prognosis in numerous tumors." (PMID 36054420, 2022). "Our results shed light on the important role of CCL14 in HCC prognosis and provided an underlying mechanism that CCL14 expression might modulate tumor immunity by regulating the infiltration of immune cells in HCC." (PMID 31927532, 2020). "This suggests that CCL14 regulates infiltration and activity of tumor-associated macrophages (TAM)." (PMID 31927532, 2020). "At the molecular level, CCL14 negatively correlates with Notch signaling and cell adhesion molecule pathways, which are closely associated with tumor migration, indicating that CCL14 may reduce tumor metastasis by inhibiting these pathways." (PMID 39030403, 2024). "Compared to other EC subtypes,EC4 exhibited elevated expression levels of multiple genes implicated in antigen presentation (HLADRB1,HLA-DRB5,and HLA-DRA),immune cell recruitment (SELP,LIFR, and ACKR1),and anti-tumor inflammation (CCL14,IFITM1)." (PMID 41394809, 2025). "CCL14 appears to be the primary recruiter of CCR1+CD14+ monocytes to the tumor mass, with high CCL14 levels correlating with poor prognosis." (PMID 40136652, 2025). "When looking for differences in CCL14 expression between certain tumor types, we used the TIMER and UALCAN databases." (PMID 39030403, 2024). "Correlation between CCL14 expression and tumor-infiltrating immune cells (TILs) and immune checkpoints." (PMID 38887558, 2024). "Sex, tumor status, and pathological stage were strongly correlated with CCL14 expression in patients with LUAD." (PMID 39030403, 2024). "This study used the TIMER database to determine how LUAD tumor-infiltrating immune cells are correlated with CCL14 expression." (PMID 39030403, 2024). "We examined the connection between CCL14, and tumor-infiltrating immune cells using TIMER, conducted a protein–protein interaction network analysis, and used gene set enrichment analysis to determine CCL14’s biological signaling pathways." (PMID 39030403, 2024). "Based on evidence from an animal xenograft tumor model, researchers have demonstrated that elevated levels of CCL14 inhibit the growth of HCC cells, regulate cell division, and promote cell death in living creatures." (PMID 39030403, 2024). "As a chemokine that activates immune cells, studies had found that CCL14 was strongly correlated with a variety of anti-tumor immune cells, including CD8+ T cells, in cancers." (PMID 38075694, 2023). "A previous study showed that CCL14 played an essential role on the chemotaxis of T lymphocytes, monocytes, and eosinophils and can act as a prognostic maker and tumor suppressor of HCC." (PMID 36245978, 2022). "On the contrary, anti-tumour chemokines, such as CCL14 and CX3CL1, were related to low NEIL3 expression in most cancers." (PMID 36612106, 2022). "As a tumor suppressor, CCL14 suppressed the proliferation and promoted the apoptosis of HCC cells via inhibiting the Wnt/β-catenin-signaling pathway." (PMID 34938730, 2021).
tumor (continued). "In MM, it has been reported that both tumor cells and BM mesenchymal stromal cells produce chemokines such as CXCL12, CCL2, CCL3, and CCL14 that promote macrophage migration to the tumor niche and polarize macrophages towards an M2-like phenotype in vitro." (PMID 33435306, 2021). "In one HCC study, researchers found that CCL14 can serve as a novel HCC tumor suppressor by regulating cell cycles and promoting apoptosis." (PMID 34424809, 2021). "In Gu’s study, CCL14 is not only a potential prognostic biomarker but also correlated with tumor immune cells infiltration in HCC." (PMID 34612781, 2021). "In summary, our results suggest that CCL14 is a potential independent prognostic biomarker for HCC that can be used to evaluate the levels of immune cell infiltration in the tumor tissues." (PMID 31927532, 2020). "We postulate that low CCL14 expression in the tumor microenvironment diminishes the Ca2+ influx and upregulates the expression of inhibitory immune checkpoint proteins, PD-1, CTLA-4 and TIM-3 on the exhausted T cells." (PMID 31927532, 2020). "Next, we investigated the correlation between CCL14 expression and the status of tumor-infiltrating immune cells based on the levels of immune marker gene expression in HCC and CHOL tissues using the TIMER and GEPIA databases." (PMID 31927532, 2020). "Although these findings show variation between the status of tumor infiltration of immune cells, the level of CCL14 expression and prognosis in different cancers, the data suggest that CCL14 expression modulates infiltration of immune cells into tumor tissues." (PMID 31927532, 2020). "The relationship between CCL14 expression and tumor immunity were analyzed by TIMER and Gene Expression Profiling Interactive Analysis (GEPIA)." (PMID 31927532, 2020). "This suggests that CCL14 plays an important role in regulating tumor immunity, and therefore influences HCC prognosis." (PMID 31927532, 2020). "CCL14 showed strong correlation with tumor-infiltrating B cells, CD4+ and CD8+ T cells, macrophages, neutrophils, and dendritic cells." (PMID 31927532, 2020). "CCL14 expression and its influence on tumor prognosis were analyzed by the ONCOMINE, Tumor Immune Estimation Resource (TIMER) and Kaplan-Meier plotter." (PMID 31927532, 2020). "Taken together, our findings indicate that CCL14 plays an important role in regulating tumor-infiltration of immune cells in HCC." (PMID 31927532, 2020). "The results show that CCL14 expression significantly correlates with tumor purity in 32 cancer types." (PMID 31927532, 2020). "In this study, we examined the expression of CCL14 in paired HCC tumor tissue and peritumor tissues." (PMID 31641099, 2019). "The results showed that CCL14 low expression in HCC tumor tissues was correlated with poor survival." (PMID 31641099, 2019). "In this study, CCL14 expression were analyzed by tissue microarray (TMA) including 171 paired tumor and peritumor tissues of patients from Zhongshan Hospital of Fudan University." (PMID 31641099, 2019). "In tumor-bearing animal models, we found tumor grew slowly in CCL14-overexpressed group than control group." (PMID 31641099, 2019). "We found for the first time that CCL14 was downregulated in HCC tumor tissues compared with peritumor tissues (P = 0.01)." (PMID 31641099, 2019). "In this study, we found that CCL14 was overexpressed in MM BM and regulated MO recruitment to the tumor bed." (PMID 26155942, 2015). "Taken together, our findings suggested that the chemokines CCL2, CCL3 and CCL14 not only regulated MO/MΦ chemoattraction, but also controlled mMΦ proliferation within the MM tumor bed and induced MΦ polarization toward mMΦs." (PMID 26155942, 2015). "In contrast, LUAD tissues showed low CCL14 protein staining in tumor cells." (PMID 39030403, 2024). "Notably, CCL14 was found to correlate with immune cell infiltration and potentially modulate the tumor immune microenvironment." (PMID 39030403, 2024).
tumor (continued). "Additionally, CCL14 has been shown to have a direct inhibitory effect on tumor cells, suppressing their proliferation and promoting apoptosis." (PMID 39030403, 2024). "The alterations in TIICs induced by CCL14 expression in the tumor microenvironment may influence tumor progression through multiple complex mechanisms, primarily including immune cell recruitment, immune cell activation, and tumor stroma remodeling." (PMID 39030403, 2024). "The tumor suppressor CCL14 was upregulated in the M2Pol subtype." (PMID 36725186, 2023). "Finally, the result was confirmed with the use of animal tumor xenograft models in vivo, which resulted in overexpression of CCL14 and led to tumor growth inhibition." (PMID 36012108, 2022). "Western blot confirmed high levels of CSF1 and CCL14 protein in UHRF1 expressing tumor cells." (PMID 35664070, 2022). "The authors revealed that CCL14 was decreased in tumor tissues compared to peritumoral tissues." (PMID 36012108, 2022). "CCL14 participates in the infiltration of the tumor by anti-cancer TILs." (PMID 34001208, 2021). "CCL14 is a tumor suppressor of HCC by modulating cell cycle and promoting apoptosis." (PMID 33777811, 2021). "Relatively low levels of CCL14 in HCC and other cancer tissues may indicate greater risk of tumor relapse after treatment and close medical supervision will be necessary for such patients." (PMID 31927532, 2020). "Furthermore, CCL14 mRNA levels correlate with the numbers of tumor-infiltrated immune cells based on the levels of markers for different immune cell types in HCC." (PMID 31927532, 2020). "This suggests a role for CCL14 in regulating tumor-infiltration of T-helper cells." (PMID 31927532, 2020). "In addition, CCL14 participates in the recruitment of monocytes into the tumor niche, especially to bone marrow, as shown on a multiple myeloma model." (PMID 33182504, 2020). "Analysis of the TIMER and GEPIA databases showed that CCL14 expression in HCC tissues significantly correlated with the expression of marker genes from tumor-infiltrating monocytes, TAMs, neutrophils, DCs, T-helper, Treg and exhausted T cells, whereas the correlation was not significant in CHOL." (PMID 31927532, 2020). "Therefore, we selected the cancer types in the TIMER database that show significant correlation between CCL14 expression and tumor purity, and in the GEPIA database that CCL14 expression is relevant to tumor prognosis." (PMID 31927532, 2020). "Dickkopf1 (DKK1), the specific inhibitor of Wnt/β-catenin-signaling pathway was used to investigate whether CCL14 inhibits the proliferation of tumor cells via Wnt/β-catenin pathway." (PMID 31641099, 2019). "We found low expression of CCL14 in HCC tumor tissues lead to shorter OS." (PMID 31641099, 2019). "The results shown overexpression of CCL14 lead to inhibiting the growth of tumor in nude mice." (PMID 31641099, 2019). "It has extensively been reported that these anti-tumour drugs impact the tumour microenvironment (TME), target human tumour-associated macrophages (hTAM), and inhibit the transcription of pro-inflammatory cytokines such as CCL2 (chemokine ligand 2), IL-6, VEGF, CCL3, CCL7, and CCL14." (PMID 38257245, 2024). "CCL14 expression has been found to correlate with the infiltration levels of various immune cells and the expression of immune checkpoint genes such as PD-L1 and CTLA-4, suggesting that CCL14 may exert its effects by modulating the tumor immune microenvironment." (PMID 39030403, 2024). "Furthermore, CCL14 might maintain the anti-tumor function of T cells by inhibiting T cell exhaustion." (PMID 39030403, 2024). "The downregulation of CCL14 associated with worse prognosis in patients associated with clinical characteristics such as males, Asians, alcohol consumers, those in early stages of tumor (stage 1+2), and those without hepatitis viral infections." (PMID 31927532, 2020).
tumor (continued). "The univariate analysis demonstrated that the CCL14 representation in cancer cells, CCL14 representation in TILs, serum level CA199, tumor depth, lymph nodes, distant metastasis, and TNM stages were correlated with overall survival." (PMID 38887558, 2024). "The mRNA expression of seven PRAN genes (CCL14, CPA3, CX3CR1, IKZF3, KIF21B, LINC00528, and SLC16A4) showed significant differences between normal and tumor samples in the advanced NSCLC cohort." (PMID 38728242, 2024). "The mRNA expression of seven PRAN genes (CCL14, CPA3, CX3CR1, IKZF3, KIF21B, LINC00528, and SLC16A4) exhibited noticeable difference between normal and tumor in NSCLC." (PMID 38728242, 2024). "For the further investigation of the expression of the three genes (CCR3, CCL14, CCL20) in HCC tissues, RT-qPCR was applied to the detection of mRNA expression of the three genes between HCC tissues and adjacent non-tumor tissues." (PMID 37545521, 2023). "The RT-qPCR results demonstrated remarkable discrepancies in the expression of CCL14, CCL20, and CCR3 between HCC and its paired adjacent non-tumor tissues." (PMID 37545521, 2023). "The tumor-infiltrating lymphocytes most closely related with CEMIP expression in BC were CCL7, CCL14, CCL20, and CXCL14." (PMID 35370456, 2022). "As expected, the expression of CCL14, CCL25, CCL26, and CCL28 were obviously related to the pathological stage, and with the aggravation of tumor malignancy, the expression of CCL25, CCL26, and CCL28 were increased while CCL14 was decreased." (PMID 34938730, 2021). "And the level of CCL14 and CD5L mRNA expressions was significantly decreased in HCC tissues, revealing CCL14 and CD5L as the potential tumour-suppressor genes." (PMID 33532508, 2021). "HCC-1 or hemofiltrate C-C motif chemokine 14 (CCL14) is a homeostatic chemokine found to promote angiogenesis and tumor progression." (PMID 33924500, 2021). "Thirdly, we did not conduct in vitro and animal experiments to confirm the role of CCL14 in the growth and progression of HCC, and its relationship with the infiltration of immune cells into the tumor microenvironment." (PMID 31927532, 2020). "The active form of CCL14 can also be broken down by atypical chemokine receptor 2 (ACKR2)/D6; however, the expression of this receptor decreases as the tumor develops." (PMID 33182504, 2020). "Subsequently, CCL14 increases the proliferation of TAM, which increases the number of these cells in the tumor niche." (PMID 33182504, 2020). "Several of these genes, including KITLG, CCL14, and CKLF, are cytokines, which possibly provide a mechanism for gene dysregulation in tumor cells to affect the immune phenotype." (PMID 31480259, 2019). "Overexpression of CCL14 by lentivirus can suppress the proliferation and promote the apoptosis of HCC cells, which lead to inhibiting tumor growth in animal xenograft tumor models." (PMID 31641099, 2019). "The inflammatory response-related genes (CCL14 (−4.52), LEP (−3.73) and PTGDS (−3.84)) showed decreased expression in the recurrence tumor tissues." (PMID 24377043, 2013). "CCL14, a chemokine known to modulate tumor immunity in various cancers, has not been thoroughly investigated in LUAD." (PMID 39030403, 2024). "Our findings indicate that CCL14 may serve as a standalone predictive biomarker for LUAD and can be used to assess the extent of immune cell infiltration in tumor tissues." (PMID 39030403, 2024). "Notably, CCL14 expression in HCC negatively correlated with PD-1, HAVCR2, and CTLA-4, suggesting its role in regulating tumor immunity." (PMID 36159990, 2022). "None of the tumor tissues analyzed in the TIMER database showed higher CCL14 expression compared with the corresponding normal tissues." (PMID 31927532, 2020). "CCL14 expression in HCC negatively correlated with expression of several immune cell markers, including exhausted T cell markers, PD-1, TIM-3 and CTLA-4, suggesting its role in regulating tumor immunity." (PMID 31927532, 2020).
tumor (continued). "Hence, our study suggests that CCL14 is a potential independent biomarker for HCC prognosis and the status of tumor immunity." (PMID 31927532, 2020). "Thus, our data indicated that MOs were attracted to the MM tumor bed by chemokines CCL3, CCL14 or CCL2 because the process was significantly attenuated by antibodies directed against these chemokines." (PMID 26155942, 2015). "Consistently, a series of chemokines, such as CCL2, CCL14, and CXCL2, as well as selectins were highly expressed in non-tumor–derived veins, whereas tumor-derived ones showed increased expression of genes related to collagen formation and ECM remodeling." (PMID 39345334, 2024). "CCL14, FYN, NOD1, and GDF10 mRNA expressions were decreased in tumor tissues compared with the adjacent non-tumor tissues." (PMID 38602568, 2024).